MUC1 (mucin 1, cell surface associated)
Diseases named in the same sentence as MUC1 in open-access papers (continued):
Sharing a sentence is not in itself a finding about the gene and the disease.
tumor (continued). "Early-phase trials targeting EGFR, MSLN (mesothelin), PSCA (prostate stem cell antigen), and MUC1 have shown preliminary evidence of tumor control, albeit with challenges related to trafficking and the immunosuppressive tumor microenvironment." (PMID 41303058, 2025). "To assess MUC1's influence on tumor spheroidal cells proliferation, we used PKH26 dye, which dilutes with each cell division." (PMID 40349179, 2025). "At tumor site, MUC1@ACS NPs released SK and Chi-Ag NPs in response to acidic environment, causing tumor cell necrosis by increasing expression levels of tetrameric MLKL, RIPK3, p-RIPK3, and, which subsequently triggered ICD." (PMID 40689201, 2025). "The co-administration of inhibitors targeting the MUC1-EGFR-ABCB1 axis with paclitaxel significantly inhibited tumor growth and relapse in a xenograft mouse model." (PMID 40699746, 2025). "In immunohistochemistry, CK7 (4/4) and MUC-1 (5/5) were positive in tumor cells, and P63 and S-100 proteins were only positive in myoepithelial cells." (PMID 40013097, 2025). "It was not until the groups were separated by sex that it was apparent that there were significant sex-based differences in tumor growth when both MUC1 antigen and TLR agonists were combined into a single set of C3-liposomes." (PMID 40284463, 2025). "Our study demonstrates that encapsulating MUC1 in C3-liposomes generates a cancer vaccine capable of eliciting an adaptive T-cell and B-cell immune response, leading to reduced tumor growth." (PMID 40284463, 2025). "In cancer progression, MUC1 contributes to facilitating tumor growth, invasion, and metastasis, as it provides resistance against apoptosis and chemotherapy." (PMID 40699746, 2025). "MUC1 also influences the tumor microenvironment by interacting with factors that promote angiogenesis, contributing to detachment from the primary site and facilitating migration and invasion." (PMID 39796763, 2025). "When examining the similarities between the Phase III trials MAGRIT, START, START2, and TIME, only one tumor antigen was encoded in each vaccine (MAGEA3 for MAGRIT, and MUC1 for START, START2, and TIME)." (PMID 41542091, 2025). "Malignant breast tumours exhibit increased expression of the MUC1 gene, which produces the CA 15-3 protein commonly used as a BC tumour marker." (PMID 41302786, 2025). "MUC1-directed CAR T-cells engineered to secrete IL-22 significantly suppressed tumor growth in vivo." (PMID 40940995, 2025). "Another heterologous prime-boost study used a vaccinia virus vector, followed by a fowlpox virus vector, to deliver CEA and MUC-1 tumor antigens." (PMID 40723238, 2025). "We successfully constructed organoids derived from the patient’s tumor samples, which expressed tumor-specific markers MUC-1 and IMP-3, as well as the proliferation marker KI-67." (PMID 40855305, 2025). "Anti-MUC1-CAR4 T cells achieve anticancer effects on MUC1-expressing CCA cells by increasing the production of anti-tumor cytokines (TNF-α and IFN-γ), pro-apoptotic proteins (granzyme B), and by inducing lysis of CCA cells." (PMID 40070825, 2025). "Given its accessibility on the cell surface and its role in tumour progression, MUC1 also presents a potential therapeutic target." (PMID 40626008, 2025). "PSCA-targeted CAR-T cells have demonstrated the capacity to delay tumor progression, whereas MUC1, particularly its glycosylated tumor-specific isoform (e.g., TnMUC1), offers a highly specific target for immunotherapy." (PMID 40904467, 2025). "The development of a new nanomaterial-based electrochemical biosensor for the detection of the MUC1 biomarker seems to be significant for early diagnosis, monitoring tumor progression, and cancer treatment." (PMID 40699746, 2025). "The presence of MUC1 in this context can enhance cancer stem cell properties and contribute to the inflammatory milieu that supports tumor growth." (PMID 40655139, 2025).
tumor (continued). "During the malignant process, MUC1 functions as an anti-adhesive molecule, thereby increasing the metastatic and invasive potential of tumour cells." (PMID 40144054, 2025). "While the MUC1-based mRNA vaccine elicited an antigen-specific cytotoxic T-cell response and enhanced T-cell infiltration into the tumor, the combination with CTLA-4 siRNA appeared to enhance this effect." (PMID 40943370, 2025). "Among mucins, increased cytoplasmic expression of MUC1 served as an independent factor of unfavourable survival and was linked with increased myeloid cell infiltrates in MMR-proficient tumours." (PMID 39966658, 2025). "The strategy of dual-targeting, such as combining MUC1 with ErbB2, provides a more refined approach, ensuring effective targeting of tumor cells while sparing normal tissues." (PMID 40312353, 2025). "In tumor cells, MUC1 exhibits altered glycosylation patterns, leading to the exposure of novel epitopes that are not present in normal tissues, making it an attractive target for immunotherapy." (PMID 40940995, 2025). "Consistent with these, our western blot results showed that MUC1 was up-regulated in OSCC tumor tissues." (PMID 39926326, 2025). "These exosomes demonstrated high specificity to MUC1‐positive cancer cells in vitro and significantly suppressed tumor growth in vivo." (PMID 40007074, 2025). "Personalized neoantigen vaccines targeting tumor-specific mutations show immunogenicity in TNBC, using antigens like HER2 and MUC1, though low tumor immunogenicity and TME tolerance limit efficacy." (PMID 40941035, 2025). "The purpose of the trial was to assess the safety, viability, and initial anti-tumor effectiveness of CAR-T cells that were modified to target MUC1." (PMID 40312353, 2025). "Several ongoing trials are testing the anti-tumor activity of MUC1-CAR-T; most of them adopted combination strategies with immune checkpoint inhibitors." (PMID 39791742, 2025). "Consistent with our previous observations, we again detected enhanced MMP9 hotspots in the periphery of MUC-1 tumor spheroids." (PMID 41310103, 2025). "Analysis of clinical SDC specimens revealed that Tn‐MUC1 was also positive in the SDC tumor cells, suggesting its potential as a cell surface target for SDC." (PMID 40844495, 2025). "The volumes of subcutaneous xenografts were dramatically increased in ectopic MUC1 expression mice compared with control mice, whereas the administration of fisetin obviously suppressed MUC1-induced tumor formation in the murine models of OSCC." (PMID 39926326, 2025). "Our previous studies have shown that the combination of MUC1 and survivin antigens induces stronger antitumor effects in multiple tumor models than vaccines with the antigen alone." (PMID 38339158, 2024). "By driving the expression of onco-immune modulatory genes, such as ENO1, MUC1, COL5A1, and IL11, FABP7 enhances tumor-associated immune suppression, particularly by facilitating the infiltration of immunosuppressive cell populations within TIME." (PMID 39596296, 2024). "This outcome is likely attributable to the highly selective expression of the MUC1 promoter in tumor cells, thereby underscoring the potential utility of rAdF35-MUC1 in CTC detection." (PMID 39886667, 2024). "To examine the role of MUC1 in immunosuppression, we knocked down MUC1 in tumour cells and determined the expression of immune checkpoint inhibitor PD‐L1." (PMID 38778448, 2024). "Mucins have garnered significant attention in tumor diagnosis and treatment, with some such as MUC1 and MUC16 being extensively utilized in the research of blood serum diagnostic markers." (PMID 38933439, 2024). "This treatment enhanced cytotoxicity of CD8+T cells from immunized mice against MUC1-positive tumor cells." (PMID 38994350, 2024). "It has been demonstrated that integrin expression and interaction with ICAM-1 are upregulated by several mucins, including MUC1, which increases the invasiveness and extravasation capacity of tumor cells." (PMID 38540735, 2024).
tumor (continued). "It proves its anti-tumor effect by inhibiting the cell cycle in the G2/M phase and decreasing the synthesis of mucin-1 (MUC1) and expression of C-X-C motif chemokine 17 (CXCL17), which stimulates the tumor microenvironment." (PMID 39339011, 2024). "Tumor site expression of MUC1 often correlates with disease progression across a wide range of cancer types." (PMID 38910324, 2024). "Despite the absence of a Tn-MUC1-positive ICC cell line, the researchers detected Tn-MUC1 in a significant percentage of ICC patient tumor tissues." (PMID 39335203, 2024). "MUC1 has an impact on the phenotypes and functions of immune cells in the tumor microenvironment (TME)." (PMID 38540735, 2024). "Twelve of these fully human monoclonal antibodies (mAb) were tested for binding to MUC1+ target cells, and three with the highest binding were further evaluated for various effector functions important for tumor rejection." (PMID 39449327, 2024). "In contrast, the gamma-synuclein gene (SNCG), associated with BC development, demonstrated a similar pattern to MUC1/Y, indicating a higher level of expression in primary cell culture compared to corresponding tumor samples." (PMID 38966179, 2024). "In these tumors, the apical transmembrane glycoprotein MUC1 [also known as epithelial membrane antigen (EMA)] is found at the tumor periphery, and the basolateral protein epithelial cell adhesion molecule (EPCAM) is found on the inward-facing membranes." (PMID 38465512, 2024). "We confirmed that Napabucasin significantly inhibited survival of the tumor cells with high MUC1 expression at lower doses compared to low MUC1 cell lines." (PMID 38326371, 2024). "Mucin 1 (MUC1) is a glycoprotein involved in the metastasis and invasion of several different tumor types." (PMID 39735530, 2024). "We demonstrated that EGFR and MUC1 were co-expressed on tumor cells in the majority of LUAD and CRC clinical samples." (PMID 39664199, 2024). "Research on the application of MUC1-related tumor vaccines in PCa has been conducted, and TG4010 has been used in clinical trials for the treatment of PCa." (PMID 39491020, 2024). "Studies have shown that the targeted O-GalNAc modification of MUC1 plays a role in changing the chemotherapy tolerance of BC and improving the efficacy of anti-tumor therapy." (PMID 38725856, 2024). "MUC1 glycoprotein contains natural IgG antibodies and endogenous anti-MUC1 antibodies have a protective effect and keep the organism in a tumor-free state through an antibody-mediated host immune surveillance mechanism." (PMID 39491020, 2024). "We showed, using loss- and gain-of-function approaches in ccRCC-derived cell lines, that MUC1 not only influences tumor progression but also induces a multi-drug-resistant profile reminiscent of the activation of ABC drug efflux transporters." (PMID 38254882, 2024). "The glycosylated MUC1 glycopeptide vaccines have high selectivity towards tumor cells, which is related to specific glycosylation patterns." (PMID 38344400, 2024). "A nanosystem of mesoporous silica, chitosan, and gold (MCM@CS@Au) targeted by aptamers for MUC-1 positive tumour cells." (PMID 39204840, 2024). "Firstly, as we showed the expression patterns of EGFR and MUC1 in a panel of normal tissues and various tumor tissues, the sample size was still limited to achieve a thorough comparison between tumor and normal tissues." (PMID 39664199, 2024). "Single-cell analysis suggested EGFR and MUC1 together had better tumor specificity than the combination of EGFR with other drug targets." (PMID 39664199, 2024). "This analysis led to the identification of genes generally associated with cancer cells (MUC1, LGALS3, UGDH, TSTA3, and GALE) or the stromal compartment (LGALS1, PSAP, LGALS9, IDS, and MGAT1) in most of the tumor types analyzed." (PMID 38384845, 2024). "Various unglycosylated or hypoglycosylated (tumor) forms of MUC1 have been tested as therapeutic vaccines in patients with advanced cancer." (PMID 39449327, 2024).
tumor (continued). "Taken together, the data convincingly showed that high expression of MUC1 in multiple tumor types sensitizes the cells to the STAT3 inhibitor Napabucasin." (PMID 38326371, 2024). "The results showed that in comparison to the iPSC-NK cells (P < 0.001) and blank control groups (P < 0.01), the xenograft tumor in the iPSC-derived MUC1-targeted CAR-NK cell group exhibited significantly slower growth." (PMID 38390321, 2024). "In this study, we showed that the overexpression of MUC1 in ccRCC cells not only promotes multi-drug resistance but also enhances tumor progression." (PMID 38254882, 2024). "Studies have shown that tumor cells expressing MUC1 exhibit upregulation of PD‐L1, and downregulation of MUC1 and PD‐L1 can exert a synergistic effect, demonstrating superior antitumor effects." (PMID 38344400, 2024). "We performed single-cell analysis based on data from an independent study to validate the co-expression of EGFR and MUC1 in cancer cells, as well as in other cells of the tumor microenvironment." (PMID 39664199, 2024). "In line with previous studies, co-expression of EGFR and MUC1 in the same tumor cells was found in most cases, including 63 (98.4%) LUAD and 76 (91.6%) CRC samples." (PMID 39664199, 2024). "A previous study confirmed that MUC1 knockdown in glioblastoma cells led to the cell cycle arrest of tumor cells in the G1 phase, thereby inhibiting tumor cell growth." (PMID 37666495, 2024). "These experimental immunotherapies targeting MUC1 are designed to induce anti-MUC1 antibodies to clear tumor cells." (PMID 38164273, 2024). "TILT-322 was able to induce cytotoxicity of CD8+ T cells, NK cells, NK-like T cells, and γδ T cells to drive killing of MUC1 expressing tumor cells." (PMID 38910324, 2024). "Mucins aid in determining the pathological biological characteristics of tumor cells, such as MUC1 (CA153) and MUC16 (CA125), which are used as biomarkers for monitoring malignant tumors." (PMID 38933439, 2024). "In concert with these results, we report that MUC1 associates with ∆Np63, SOX2, and NOTCH3 expression in HNSCC tumor cells as determined by single-cell RNA sequencing (scRNA-seq) analysis." (PMID 38619287, 2024). "Accompanying the reduced tumor volume seen in mice tumors treated with TILT-322 was the reduced expression of MUC1, which was evident in both intratumoral and intravenous." (PMID 38910324, 2024). "As an example, the aberrant O-linked glycosylation of MUC1 in carcinomas can alter the interaction of MUC1 with glycan binding receptors, consequently affecting the tumor-immune interplay." (PMID 38881904, 2024). "MUC1 induces angiogenesis in tumor microenvironments by increasing the expression of neuropilin-1(NRP1, a co-receptor of VEGF) and its ligand VEGF51." (PMID 38164273, 2024). "Characteristically overexpressed in EOC, MUC1 is primarily found on the surface of tumor cells and is underglycosylated, exposing epitopes concealed in non-malignant cells." (PMID 39033780, 2024). "The GSEA data indicated that MUC1 was also involved in other aspects of tumor biology, such as regulation of immune cell infiltration and angiogenesis induction." (PMID 38540735, 2024). "MUC1 has been shown, in particular, to be overexpressed in two-thirds of cancers and induce cell growth and tumor progression through the activation of various signaling pathways." (PMID 38254882, 2024). "MUC1, a transmembrane mucin glycoprotein, is commonly detected in epithelial cells and has been widely studied as a tumor marker." (PMID 38893239, 2024). "MUC1 modulates chronic inflammation, but little is known about how it controls the tumor microenvironment (TME), particularly in ccRCC." (PMID 38540735, 2024). "It has been proposed that aberrant expression of MUC1 facilitates detachment of tumor cells from the primary tumor because MUC1 mediates anti-adhesion activity by interfering with cell-to-cell and/or cell-to-extracellular matrix interactions." (PMID 38592620, 2024).
tumor (continued). "Over-expression of MUC-1 was found in many cancers and was related to increased tumor invasiveness and poor prognosis." (PMID 38474142, 2024). "To access the reliability and validity of BLI to detect the engraftment and growth of PDAC tumor cells, we used the Muc1-null PDAC model (designated KCKO-Luc)." (PMID 38165848, 2024). "Alcian blue histochemical staining was used to confirm the presence of mucin, dominantly in the extracellular space (blue staining), while immunohistochemical staining with anti MUC1 antibody was used for the same purpose (membranous staining of tumor cells)." (PMID 38674308, 2024). "We then confirmed that the expression patterns of EGFR and MUC1 in tumor tissues by immunohistochemistry (IHC)." (PMID 39664199, 2024). "MUC1 can induce immune response in CTLs while inhibiting the cytotoxic effects of immune active cells on tumor cells." (PMID 39491020, 2024). "In tumors, the long O-GalNAc branch of MUC1 is truncated to form a classic tumor antigen, making it an emerging target for immunotherapy." (PMID 38725856, 2024). "GT-00AxIL15 is a novel interleukin-15-based immunocytokine targeting a tumor-specific, glycosylated epitope of MUC1 (TA-MUC1)." (PMID 38338686, 2024). "The dendrimers were functionalized with MUC-1 aptamers to selectively deliver the therapeutic platform (gold nanoparticles and curcumin) to the tumor tissue." (PMID 38399238, 2024). "We obtained a reliable relationship between the aggressive nature of tumor growth, an increased level of pro-inflammatory cytokines, a low level of free estradiol, and the suppressed expression of salivary MUC1." (PMID 39456554, 2024). "In one investigation, AdVs were employed as a therapeutic tool for purging MM cells, showing their ability to deliver the TK gene into MM cells using the DF3/MUC1 tumor promoter, with tumor cell transduction observed to be highly efficient (>80%)." (PMID 39539548, 2024). "Under pathological circumstances, MUC1 acts in a pro-inflammatory way, producing positive conditions for tumor growth." (PMID 38540735, 2024). "Targeting MUC1 has been shown to be an effective way to induce tumor cell death in vivo and in vitro models." (PMID 38164273, 2024). "In this context, we focused our attention on MUC1, a membrane-bound mucin, which is overexpressed in two-thirds of cancers and known to play a role in tumor progression, chemoresistance, and the establishment of an immunosuppressive microenvironment." (PMID 38254882, 2024). "The antibodies induced by this vaccine exhibited robust affinity toward tumor cells expressing MUC1 and elicited antigen‐specific CTLs and robust antibody response, leading to tumor eradication." (PMID 39611045, 2024). "MUC1 is a glycoprotein involved in the proliferation, metabolism, metastasis and invasion of multiple tumor types, and overexpressed in various epithelial cancers with aberrant glycosylation." (PMID 39664199, 2024). "They found that MUC1-DEX induced high MUC1-specific immunoglobulin G antibody titers with strong binding affinity to MUC1-positive tumor cells in vivo." (PMID 38994350, 2024). "Based on this theory, in recent years, many studies have found the target of MUC1 anti-tumor vaccine, and the results showed that the survival rate was improved and the metastatic foci were reduced in the mouse model." (PMID 38699634, 2024). "In this work, we screened TAA targets using a single-cell analysis pipeline, and found a potential target MUC1 with high expression in tumor cells and relatively low or undetectable expression in normal tissues." (PMID 39664199, 2024). "In the present study, IHC staining showed that P. gingivalis treatment inhibited MUC1 expression and promoted caspase 3 expression, indicating an increase in tumor cell apoptosis." (PMID 37666495, 2024). "Immunohistochemical analyses showed that MUC1 protein was expressed in the cytoplasm of the tumor cells." (PMID 38592620, 2024).